CTBP2 (C-terminal binding protein 2)
Diseases named in the same sentence as CTBP2 in open-access papers (continued):
Sharing a sentence is not in itself a finding about the gene and the disease.
breast carcinoma (continued). "Our findings suggest that CtBP2 promotes cell proliferation by inhibiting p16INK4A, resulting in a shorter transition of the cell cycle in breast cancer cells." (PMID 28412731, 2017). "A better understanding of the molecular mechanism of CtBP2 in breast cancer development and progression provides novel therapeutic strategies for breast cancer patients." (PMID 28412731, 2017). "In addition to shRNA knockdown of CtBP2 in BON1 PNET cells, we used CRISPR-Cas9 to knock out (KO) CtBP2 in the MDA-MB-231 breast cancer cell line to further test the regulation of nuclear translocation of Bcl-xL by CtBP2." (PMID 37163116, 2023). "The primary RAI2 amino acid sequence has two highly orthologically conserved sequences (ALDLS) in the internal region (amino acids 316–320 and 342–346 in human sequence) of the RAI2 protein, and It was reported that RAI2 can interact with CtBP2 by ALDLS domain in breast cancer." (PMID 35299743, 2022). "By integrating metabolomics and transcriptomics in a triple-negative human breast cancer cell line, we show that genetic and pharmacological down-regulation of CtBP2 strongly reduces cell proliferation by modulating the redox balance, nucleotide synthesis, ROS generation, and scavenging." (PMID 34680207, 2021). "The expression of CtBP2 was increased in breast cancer tissues and cell lines." (PMID 28412731, 2017). "The expression of CtBP2 was positively related to Ki-67 in breast cancer specimens." (PMID 28412731, 2017). "This study also showed that CtBP2 is related to histologic grade, metastasis and tumor size, which implies that CtBP2 may be involved in the proliferation and migration of breast cancer." (PMID 28412731, 2017). "Moreover, we found that the level of p16INK4A was inversely related to the level of CtBP2 in both breast carcinoma specimens and cell lines of breast cancer." (PMID 28412731, 2017). "The role and mechanism of CtBP2 in breast cancer remains to be elucidated." (PMID 28412731, 2017). "In summary, our results demonstrate that CtBP2 might contribute to the progression of breast cancer by promoting cell proliferation, enhancing cell migration or invasion and inhibiting the expression of p16INK4A." (PMID 28412731, 2017). "Moreover, gain-of-function experiments showed that CtBP2 suppressed p16INK4A and matrix metalloproteinase-2, subsequently enhancing the migration in breast cancer." (PMID 28412731, 2017). "Therefore, the present study is aimed to investigate the role and mechanism of CtBP2 in human breast cancer." (PMID 28412731, 2017). "However, the molecular mechanism of CtBP2 in human breast cancer is unclear." (PMID 28412731, 2017). "In breast cancer, CTBP1/2 acts as an epigenetic effector downstream of elevated NADH, suggesting that CTBP2 is involved in promoting energy production in cancer cells." (PMID 38698344, 2024). "It was reported that RAI2 can interact with CtBPs, especially CtBP2, through ALDLS domains and inhibit the transcriptional repression effect of CtBP2 on target genes in breast cancer." (PMID 35299743, 2022). "For instance, CTBP2 was demonstrated to facilitate the development of ESCC and breast cancer through negatively regulating p16 (INK4A), a tumor suppressor gene product." (PMID 29147064, 2017). "However, CtBP2 expression was not related to the age, histology, estrogen receptors (ER), progesterone receptors (PR) or HER2 status in patients with breast cancer." (PMID 28412731, 2017).
colorectal cancer (8 papers, 2018 to 2025). A primary or metastatic malignant neoplasm that affects the colon or rectum. "Elevated levels of G9a and CtBP2 are each associated with poor prognosis in colorectal cancer, and our data now suggest that they cooperate functionally at the chromatin level." (PMID 41419197, 2025). "We continued investigating the function of co-regulator CtBP2, and show that CtBP2 mediates ER stress-induced loss of stemness which supports the intestinal stem cell state in homeostatic stem cells and colorectal cancer cells." (PMID 33972635, 2021). "In colorectal cancer cells, disrupting the CtBP2-G9a interface reduces H3K9me2 deposition at target promoters such as PTEN, leading to transcriptional derepression, attenuation of oncogenic signaling, and impaired tumor cell proliferation." (PMID 41419197, 2025). "Together with our biochemical and structural data, these findings demonstrate that CtBP2-mediated stimulation of G9a constitutes a critical epigenetic mechanism driving transcriptional silencing in colorectal cancer." (PMID 41419197, 2025). "In colorectal cancer, miR-556-5p inhibits cell proliferation and migration by targeting CTBP2, which is involved in the EMT signaling pathway." (PMID 37670963, 2023). "For example, in colorectal cancer, the interaction of CtBP2 with TCF-4 can activate its transcription activity, leading to activation of the downstream target gene β-catenin and resulting in cell migration." (PMID 30151388, 2018). "CTBP2 was hinted to constitute an essential facet of tumor development in colorectal cancer." (PMID 34781990, 2021). "In colorectal cancer (CRC) cells, CtBP2 and G9a co-occupy the PTEN promoter, where disruption of their interface reduces H3K9me2 deposition, derepresses PTEN expression, attenuates PI3K-AKT signaling, and impairs CRC cell proliferation." (PMID 41419197, 2025).
Obesity (8 papers, 2017 to 2025). Accumulation of substantial excess body fat. "Here, we initially screened the coding regions of CTBP2 in patients with AN and severe obesity reporting 24 variants located in the RIBEYE specific exon (A-domain)." (PMID 39511451, 2025). "We herein demonstrate that monomeric CtBP2, the predominant form in the metabolic milieu associated with obesity, represses the transcriptional activity of PPARα." (PMID 37286039, 2023). "The metabolite imbalance between NADH/NAD+ and fatty acyl-CoA predisposes to obesity-associated metabolic disturbances through inactivation of CtBP2." (PMID 34728642, 2021). "MiR-342-3p is considered as an obesity-associated microRNA, since it positively regulates adipogenesis of adipose-derived mesenchymal stem cells by suppressing CtBP2 and releasing the key adipogenic regulator C/EBPα from CtBP2 binding." (PMID 30717412, 2019). "To identify genetic variants that might be implicated in AN and/or weight regulation, we performed a mutation screen of CTBP2 in 95 female patients with AN and 92 children and adolescents with severe obesity (including 48 females)." (PMID 39511451, 2025). "The latest research indicates that Ctbp2, as a key metabolite receptor, plays a crucial role in the pathogenesis of metabolic imbalance and obesity, suggesting the potential of targeting Ctbp2 for the treatment of metabolic diseases." (PMID 40140769, 2025). "Further, one recent study revealed that the proteins of Ctbp2 are inactive in obesity and showed a relevance between its inactivation and pathogenesis of obesity-related metabolic disturbances." (PMID 39511451, 2025). "It was reported that CTBP2’s protein expression was reduced in pancreatic islets cells in various mouse models, but also in human obesity." (PMID 39511451, 2025). "This localization was unexpected as to date no study had linked RIBEYE to body weight-related traits, though the role of CTBP2 in obesity is well established." (PMID 39511451, 2025). "Several mechanisms are known for miR-144-3p to promote adipogenesis: from suppressing the FOXO1 and reducing its regulation of adiponectin to stimulating differentiation of adipocytes by direct targeting Klf3 and CtBP2, protective factors against obesity." (PMID 38139235, 2023). "Our findings demonstrated a sequential event whereby CtBP2 adopts a monomeric configuration in response to obesity-induced metabolic alterations, resulting in binding to PPARα." (PMID 37286039, 2023). "In other words, CtBP2 bound to PPARα on a per molecule basis tended to be increased in mice with genetic obesity (1.6-fold increase based on our densitometric quantification, p = 0.10)." (PMID 37286039, 2023). "As demonstrated in our previous finding that CtBP2 adopts a monomeric state in obese liver due to acyl-CoA deposition, the findings in this study further indicate that CtBP2 represses the transcriptional activity of PPARα particularly in the liver of obesity." (PMID 37286039, 2023). "In conclusion, we identified a novel interaction between CtBP2 and PPARα that responds to metabolic alterations induced by obesity." (PMID 37286039, 2023). "Having observed the therapeutic potentials of CtBP2 activation in obesity, we decided to further explore the structure–function relationships in CtBP2 protein." (PMID 34728642, 2021). "In mice with genetic obesity, CtBP2/FoxO1 interaction was dramatically (~90%) reduced as well as in diet-induced obese mice." (PMID 34728642, 2021). "In the pathological conditions induced by obesity, CtBP2 dimer formation is disrupted upon binding to fatty acyl-CoAs resulting in dissociation from transcription factors." (PMID 34728642, 2021). "Observing the dissociation of CtBP2 from FoxO1 in obesity, a question arises regarding in which cellular compartment this regulatory step occurs." (PMID 34728642, 2021). "The observation of robust inactivation of CtBP2 in obesity prompted us to utilize a liver-specific CtBP2-deletion model in mice." (PMID 34728642, 2021).
Obesity (continued). "A recent study provided further evidence for CTBP2’s role in obesity." (PMID 39511451, 2025). "In this context, the genetic deletion of CtBP2 may mimic obesity-induced conformational alterations of CtBP2." (PMID 37286039, 2023). "We next examined CtBP2–PPARα complex formation in the livers of multiple animal models of obesity." (PMID 37286039, 2023). "The CtBP2–PPARα interaction may provide a basis to better understand the pathogenesis of obesity for the development of novel therapeutic approaches." (PMID 37286039, 2023). "Importantly, inactivation of CtBP2 is the critical defect in the pathogenesis of obesity leading to metabolic inflexibility while activation of CtBP2 can be a therapeutic approach for the obesity-induced metabolic diseases." (PMID 34728642, 2021). "Replenishment of CtBP2 normalized fasting blood glucose levels in obese mice without inducing any changes in body weights and improved glucose tolerance although the degree of obesity was modest." (PMID 34728642, 2021). "Conversely, activation of CtBP2 ameliorates diabetes and hepatic steatosis in obesity." (PMID 34728642, 2021). "Their results showed that CtBP2 can monitor cellular redox status and maintain coordinated metabolic homeostasis, and that the dysfunction of CtBP2 may be a key point in the development of obesity." (PMID 38932279, 2024). "Importantly, CtBP2 recruitment to those promoters was also increased in obesity." (PMID 37286039, 2023). "Liver autopsy samples showed diminished CtBP2/FoxO1 interaction in the liver of subjects with obesity, suggesting that our findings could be extrapolatable and relevant to human disease despite the imperfect qualities of samples related to the postmortem changes." (PMID 34728642, 2021). "Since CtBP2 activation in hepatocytes downregulated gluconeogenic and lipogenic gene expression in vitro and the activity of CtBP2 is diminished in obesity, we investigated whether exogenous supplementation of CtBP2 can improve the metabolic profile of obese mice in vivo." (PMID 34728642, 2021). "Both CTBP2 and NBEAL1 show altered hypothalamic expression in response to fasting and diet-induced obesity and are postulated to act upon or at synapses." (PMID 28093506, 2017). "Interestingly, CtBP2 formed an interaction with SREBP1 in the liver of lean mice which was diminished in both genetic obesity and diet-induced obesity." (PMID 34728642, 2021). "We further examined whether the diminished binding of CtBP2 observed in obesity is specific to FoxO1 and SREBP1 by detecting the interaction of CtBP2 with a known partner, zinc-finger protein FOG family member 1 (ZFPM1), that was again decreased in the liver of obesity (~96%)." (PMID 34728642, 2021). "However, it may not faithfully recapitulate obesity since monomeric CtBP2 is rather a gain-of-function state in the interaction with PPARα." (PMID 37286039, 2023). "Thus, genetic deletion of CtBP2 may not faithfully mimic obesity-induced allosteric alterations of CtBP2." (PMID 34728642, 2021).
esophageal squamous cell carcinoma (5 papers, 2017 to 2023). Esophageal squamous cell carcinoma (ESCC) is a type of esophageal carcinoma (EC) that can affect any part of the esophagus, but is usually located in the upper or middle third. "LncRNA NEAT1 sponges miR-129 to regulate the progression of esophageal squamous cell carcinoma via increasing CTBP2 expression." (PMID 32351327, 2020). "LncRNA nuclear paraspeckle assembly transcript 1 (NEAT1) sponged to miR-129, leading to the depression of CTBP2 and regulated the esophageal squamous cell carcinoma (ESCC) cell viability and invasion." (PMID 34068010, 2021).
gastric cancer (5 papers, 2017 to 2024). A primary or metastatic malignant neoplasm involving the stomach. "Another study pointed out that the expression of CtBP2 is inversely correlated with the disease-free progression of gastric cancer, indicating that CtBP2 plays a significant role in the progression of gastric cancer." (PMID 38932279, 2024). "This suggests that MAP3K8 may influence gastric cancer progression by regulating the expression of CtBP2." (PMID 38932279, 2024). "Additionally, CTBP2 was found to be overexpressed in gastric cancer (GC) and correlated with poor prognosis and accelerate GC tumorigenesis and metastasis." (PMID 29147064, 2017). "However, few studies on CtBP2 in gastric cancer (GC) have been performed." (PMID 28404932, 2017).
colon cancer (4 papers, 2018 to 2022). "We generated HCT116 colon cancer cells genetically deficient for CtBP2 using CRISPR knockout techniques, and compared the effect of 4-Cl-HIPP treatment vs. CtBP2 knockout on tumorsphere growth." (PMID 30197752, 2018). "Depletion of CtBP2 inhibited, while its overexpression enhanced, CSC growth and self-renewal in colon cancer." (PMID 35299743, 2022). "Recent results add to evidence of a link between CtBP and cancer progression by showing increased survival in mice models for colon cancer (APCmin/+) and pancreatic adenocarcinoma (CKP) when CtBP2 levels are lowered by CtBP2+/- heterozygosity." (PMID 33524397, 2021). "Thus, 4-Cl-HIPP can phenocopy CtBP2 knockout and inhibit the Wnt target and TIC marker LGR5, and also attenuate expression of the key oncogenic Wnt pathway target c-Myc in human colon cancer cells." (PMID 30197752, 2018).
diabetes (4 papers, 2012 to 2023). "We reported the therapeutic potential of CtBP2 dimerization in obese liver to ameliorate diabetes as well as steatosis." (PMID 37286039, 2023). "Conversely, activation of CtBP2 in obese liver ameliorates diabetes and hepatic steatosis." (PMID 37286039, 2023). "The ALA201HIS mutant CtBP2 more potently ameliorated diabetes and hepatic steatosis than wild-type CtBP2 without inducing any changes in body weights." (PMID 34728642, 2021).
hepatocellular carcinoma (4 papers, 2017 to 2024). A malignant tumor that arises from hepatocytes. "On the other hand, CtBP2 may inhibit the expression level of oncogenes through the formation of transcriptional co-repressors, thereby promoting hepatocellular carcinoma." (PMID 38932279, 2024).
adenoma (3 papers, 2018 to 2025). A neoplasm arising from the epithelium. "To show that depletion of CtBP2 functionally affects stemness in human adenoma cells with a mutation in APC, we made use of colonic epithelial organoids derived from adenomas of patients with familial adenomatous polyposis (FAP)." (PMID 33972635, 2021). "Comparative analysis between adenoma with adenocarcinoma samples showed that ARRB1, CTBP1 and CTBP2 are overexpressed in adenoma." (PMID 40362431, 2025). "ARRB1, CTBP1 and CTBP2 were genes identified based on the top 20 frequently occurring genes and are upregulated in adenoma samples." (PMID 40362431, 2025). "As expected, CtBP2 levels were significantly elevated in adenomas compared to healthy tissue, supporting a role for CtBP2 in human adenomagenesis." (PMID 33972635, 2021). "This suggests that CtBP2 is also crucial for stemness in APC deleted cell of adenomas from FAP patients, at least in vitro." (PMID 33972635, 2021). "As CtBP2 is targetable by an inhibitor of its dehydrogenase domain, understanding CtBP2’s role in adenoma formation is necessary to optimize CtBP-targeted therapies in Apc mutated human neoplasia." (PMID 30197752, 2018). "ARRB1 (p = 2.79 × 10−5), CTBP1 (p = 1.33 × 10−5) and CTBP2 genes (p = 0.0002) exhibited notable upregulation in adenoma, whereas COL1A2 (p = 0.0075), CEBPZ (p = 0.0057), MED10 (p = 0.0196) and PAWR genes (p = 0.00215) showed significant upregulation in adenocarcinoma." (PMID 40362431, 2025). "In adenoma, ARRB1, CTBP1 and CTBP2 were overexpressed, suggesting their involvement in early tumorigenesis, whereas in CIS, RPS3A and COL4A5 were overexpressed, suggesting their involvement in the transition from benign to malignant stage." (PMID 40362431, 2025). "Interestingly, the few adenomatous polyps from Ctbp2+/-Apcmin/+ mice exhibited significantly diminished CD133+ expression, along with markedly less proliferative potential, as determined by Ki-67 staining, towards the edge of the polyp, as compared with Apcmin/+ adenomas." (PMID 30197752, 2018).
deafness (3 papers, 2014 to 2023). An inherited or acquired condition characterized by the complete loss of the ability to hear from one or both ears. "Some of them (e.g., ARID5B, CTBP2, and FTO) were previously identified as causal loci of Mendelian forms of deafness." (PMID 37165447, 2023). "Furthermore, the percentage of HCs that had CtBP2 puncta after ATOH1 treatment was not different to those examined after four days of deafness." (PMID 25036727, 2014).
Familial adenomatous polyposis (3 papers, 2018 to 2022). Familial adenomatous polyposis (FAP) is characterized by the development of hundreds to thousands of adenomas in the rectum and colon during the second decade of life. "And CtBP2 haplo-insufficiency could rescue polyposis induced by mutation of APC in the min mouse model of the human Familial Adenomatous Polyposis." (PMID 35299743, 2022). "It was reported that CtBP2 haplo-insufficiency could rescue polyposis induced by mutation of APC in the min mouse model of the human disease Familial Adenomatous Polyposis." (PMID 35299743, 2022). "C-terminal binding protein 2 (CtBP2) drives intestinal polyposis in the Apcmin mouse model of human Familial Adenomatous Polyposis." (PMID 30197752, 2018). "The role of altered activity of transcription factor CtBP2 was further examined by modification of its expression levels using CAG-rtTA3-CtBP2 overexpression in small intestinal organoids, shCtBP2 knockdown in LS174T cells, and familial adenomatous polyposis patient-derived organoids." (PMID 33972635, 2021).
glioma (3 papers, 2019 to 2023). A benign or malignant brain and spinal cord tumor that arises from glial cells (astrocytes, oligodendrocytes, ependymal cells). "In glioma tissues, reportedly, miR-338-5p impedes tumor cell proliferation and invasion by targeting CTBP2." (PMID 34937497, 2022).
hearing loss (3 papers, 2014 to 2022). "Furthermore, variation at the CTBP2 locus has also recently been identified in a genome wide association study of self-reported hearing loss in the UK Biobank Cohort suggesting it may play a role in auditory maintenance." (PMID 35165318, 2022).